MARK4 (microtubule affinity regulating kinase 4)
Diseases named in the same sentence as MARK4 in open-access papers (continued):
Sharing a sentence is not in itself a finding about the gene and the disease.
cancer (31 papers, 2016 to 2025). A tumor composed of atypical neoplastic, often pleomorphic cells that invade other tissues. "The overexpression of microtubule affinity-regulating kinase 4 (MARK4) is a common cause of malignancies, making it a special target for antitumor action." (PMID 38686058, 2024). "Overexpression of MARK4 is associated with various cancers, metastatic transitions, aberrant and uncontrolled neuronal migrations, and microtubule dynamics disturbance." (PMID 35936719, 2022). "It is known that a kinase, MARK4, is associated with different cancers and uncontrolled neural migration, and is a potential therapeutic drug target for cancer and AD therapy." (PMID 35164383, 2022). "On the other hand, Microtubule Affinity Regulating Kinase 4 (MARK4) is associated with various cancer types, uncontrolled neuronal migrations, and disrupted microtubule dynamics." (PMID 34681645, 2021). "Citral potentially binds to MARK4 and inhibits its kinase activity, and is being considered an effective strategy to prevent the growth of cancer cells and other MARK4 associated diseases." (PMID 35052524, 2021). "It is reported that microRNA (miR)-515-5p regulates MARK4 in cancer cells, and miR-515-5p/MARK4 axis is implicated in regulating cancer cell migration and metastasis." (PMID 34037089, 2021). "In light of all these important roles of MARK4, it is currently considered an attractive drug target especially for AD and some of the associated cancers." (PMID 32443670, 2020). "Our study provides a rationale for the therapeutic evaluation of RA and RA-based inhibitors in MARK4 associated cancers and other diseases." (PMID 32587267, 2020). "MARK4 also regulates miR515-5p, implicated in metastasis and cancer cell migration." (PMID 37795023, 2023). "MARK4 and Mimosin, Quercetin, and Resveratrol could potentially interact with critical cancer-associated proteins." (PMID 35936719, 2022). "Overexpression of MARK4 is associated with cancers and neurodegenerative diseases." (PMID 34681645, 2021). "Alterations in MARK4 expression hamper the cell cycle and eventually cause cancer." (PMID 35052524, 2021). "α-Mangostin (1–50 μM) inhibited MARK4 kinase activity, leading to decreased cell proliferation, induction of apoptosis, and G0/G1 cell cycle arrest in cancer cells." (PMID 39595559, 2024). "Khan and colleagues identified α-mangostin as a promising inhibitor of microtubule affinity-regulating kinase 4 (MARK4), which is overexpressed in various cancers." (PMID 39595559, 2024). "Due to the immense importance of MARK4 in cancers, AD, and other disorders, it is gaining significant attention as a druggable target." (PMID 37795023, 2023). "MARK4 can promote the proliferation and migration of cancer cells by inhibiting Hippo signaling, the targeted inhibition of which is a strategy to treat cancers." (PMID 37889117, 2023). "MARK4 is overexpressed in various cancer types including breast cancer, playing a vital role in the growth, progression, and apoptotic evasion of cancer cells." (PMID 37836581, 2023). "These inhibitors decrease the growth and proliferation of various cancer cell types, emphasizing the significance of MARK4 inhibitors in improving the outcomes of MARK4-related cancers." (PMID 35936719, 2022). "These inhibitors reduce the growth and proliferation of various cancer cell types, highlighting the importance of MARK4 inhibitors in improving the outcomes of malignancies." (PMID 35936719, 2022). "Based on previous studies, MARK4 has been identified as a potential therapeutic target for cancer and other disorders." (PMID 35936719, 2022). "The present study establishes irisin as an inhibitor of MARK4, highlighting its role in cancer and AD therapy." (PMID 34681645, 2021). "MARK4 is exploited as a potential drug target for cancer, neurodegenerative disorders, and metabolic disorders highlighting its clinical significance." (PMID 32443670, 2020).
cancer (continued). "Based on a series of in silico and in vitro screening assays, two hydrazone molecules were selected which possess considerable inhibition and high binding affinities for MARK4 and decrease the growth and proliferation of cancer cells." (PMID 35520423, 2020). "Overexpression of MARK4 is involved in cancer progression, metastasis, guiding neuronal migration, cell polarity, microtubule dynamics, apoptosis, cell cycle regulation, cell signaling and differentiation." (PMID 32587267, 2020). "Due to its significant role in the development and progression of cancer, different in-house libraries of synthesized small molecules were screened to identify potential MARK4 inhibitors." (PMID 35520423, 2020). "miR-515-5p controls cancer cell migration throughmodulation of MARK4 (microtubule affinity-regulating kinase 4) 3’-UTR region." (PMID 31606975, 2020). "Microtubule affinity regulating kinase (MARK4) is a potential drug target for different types of cancer as it controls the early step of cell division." (PMID 32587267, 2020). "Further, fluorescence binding studies, isothermal titration calorimetry (ITC) and apoptosis studies suggested a high binding affinity of RA with MARK4 which subsequently induces apoptosis in MARK4 overexpressing cancer cells." (PMID 32587267, 2020). "Microtubule affinity regulating kinase 4 (MARK4) becomes a unique anti-cancer drug target as its overexpression is responsible for different types of cancers." (PMID 30737440, 2019). "Other studies have shown that citral treatment can lead to reduction of expression of prostemness and prosurvival factors such as aldehyde dehydrogenase 1A3 (ALDH1A3) and microtubule affinity regulating kinase 4 (MARK4) in cancer, respectively." (PMID 29765461, 2018). "The opposite correlation existed for MARK4 expression, with high expression of this kinase correlating with poorer survival in these two cancer types." (PMID 26882547, 2016). "Taken together, these data demonstrate the importance of miR‐515‐5p/MARK4 regulation in cell migration and metastasis across two common cancers." (PMID 26882547, 2016). "Their 500 ns all-atom simulations and molecular docking showed that RA forms stable non-covalent interactions with important residues in the MARK4 active site, indicating that RA may prevent MARK4 from playing a role in the development of cancer." (PMID 40427522, 2025). "MARK4 plays a role in the development of DM and cancer among other neurodegenerative diseases; linagliptin is a potential inhibitor of MARK4 and may act as a molecule against MARK4-mediated neurodegenerative diseases." (PMID 39177655, 2024). "MARK4 inhibitors decrease the growth and proliferation of a range of cancer cell types, implying that they could help patients with cancer." (PMID 35936719, 2022). "MARK4 inhibitors limit the growth and proliferation of various cancer cell types, suggesting that they may be effective in improving cancer outcomes." (PMID 35936719, 2022). "MiR-515-5p modulates migration of cancer cells by targeting MARK4." (PMID 34774083, 2021). "Thus, pharmacologically or through exercise-induced irisin levels, there can be a therapeutic strategy to treat MARK4–directed cancers and neurodegenerative diseases." (PMID 34681645, 2021). "All these studies established MARK4 as a potential druggable target for cancer and other disorders." (PMID 35520423, 2020). "miR-515-5p controls cancer cell migration through MARK4 regulation." (PMID 31057422, 2019). "Furthermore, our observations imply that targeting of MARK4 by rutin and vanillin may be an efficient approach to combat with the pathophysiology of cancer and neurodegenerative disorders." (PMID 28842631, 2017). "It is reported that miR-515-5p directly targets MARK4 3′ UTR, represses its expression, and participates in regulating the biological behaviors of cancer cells." (PMID 34037089, 2021).
cancer (continued). "In addition, inhibition of MARK4 by RA provides a newer avenue for cancer treatment as its expression is found to be enhanced in many cancers This study proved that RA may be employed as potent MARK4 inhibitor to control cancer cell growth and induction of apotosis." (PMID 32587267, 2020). "Microtubule affinity regulating kinase 4 (MARK4) is a Ser/Thr kinase belonging to AMPK-like family, has recently become an important drug target against cancer and neurodegenerative disorders." (PMID 28842631, 2017). "MARK4, a Ser/Thr kinase belonging to AMPK-like family, has recently become an important drug target against neurodegenerative diseases, cancer, obesity and other related metabolic disorders." (PMID 28842631, 2017). "Also, as MARK4‐specific inhibitors have now been developed 21, our data suggest that these molecules may be useful in the clinic to prevent metastatic dissemination of lung, breast and possibly other cancers." (PMID 26882547, 2016). "In terms of mRNA expression, microtubule affinity regulating kinase 4 (MARK4) and Laminin Subunit Gamma 2 (LAMC2), with the highest dynamic weights in sample 66, may become potential high-efficiency targets for cancer treatment." (PMID 37889117, 2023).
neurodegenerative disease (10 papers, 2018 to 2025). A disorder of the central nervous system characterized by gradual and progressive loss of neural tissue and neurologic function. "Microtubule affinity-regulating kinase 4 (MARK4) is also a well-known gene linked to neurodegenerative disease." (PMID 37550059, 2023). "Studies have shown an association of MARK4 expression with neurodegenerative diseases, such as AD and PD, with MARK4 being present in significantly higher expression levels in neurodegenerative disease cases." (PMID 37287673, 2023). "Further investigation of glial changes in response to MARK4 suppression in other neurodegenerative disease models may reveal novel aspects of the mechanisms underlying astroglia activation in disease pathogenesis." (PMID 38712317, 2024). "Final compounds were then assessed in-vitro against the MARK4 enzyme, which has emerged as a potential target to combat neurodegenerative diseases." (PMID 39902071, 2024). "Due to the various important roles of MARK4 in neurodegenerative diseases, MARK4 is considered an attractive drug target; therefore, its inhibition can be a therapeutic strategy for treating neurodegenerative disorders." (PMID 34681645, 2021). "Numerous reports have suggested MARK4 as one of the best targets for AD therapy and other neurodegenerative diseases." (PMID 34681645, 2021). "Hence, targeting MARK4 by serotonin opens a “new gate” in managing the clinical manifestations of neurodegenerative diseases such as AD and dementia." (PMID 35955902, 2022). "Thus, inhibiting MARK4 can be considered essential to cure some neurodegenerative diseases, including AD." (PMID 35955902, 2022). "Therefore, we propose that synapse instability might be one of the early events in neurodegenerative diseases like AD and that increase in Par-1/ MARK4 could facilitate the instability and hasten the demise of synapses." (PMID 30382129, 2018).
tumor (8 papers, 2016 to 2026). "Taken together, these results demonstrate that KMT5A-dependent SNIP1 methylation promotes TNBC tumor and lung metastasis by activating MARK4 transcription and subsequent modification of the Hippo/YAP signaling pathway." (PMID 35449131, 2022). "In the present work, it was demonstrated that miR-515-5p exerted its tumor-suppressive function in GC by inhibiting MARK4, and this regulatory relationship between miR-515-5p and MARK4 was consistent with previous reports (11,26, )." (PMID 34037089, 2021). "In summary, these results showed that LINC00673 promoted tumor cell growth at least in part by acting as a ceRNA for miR-515-5p and thus regulating the MARK4/Hippo signaling pathways." (PMID 31623640, 2019). "Mechanistically, LINC00673 promotes tumor proliferation by sponging miR-515-5p to regulate MARK4 and then inhibits the Hippo signaling pathway." (PMID 31623640, 2019). "In all, we showed that LINC00673 is activated by YY1 and acts as a sponge for miR-515-5p, regulating MARK4, inactivating the Hippo signaling pathway, and resulting in tumor progression." (PMID 31623640, 2019). "Having previously demonstrated the role of miR‐515‐5p as an ER‐positive breast cancer tumour suppressor 11, here we show that miR‐515‐5p inhibits cell migration via its targeting of MARK4." (PMID 26882547, 2016). "In principle, any one of these ARKs could exert tumour suppressor effects of LKB1, and indeed there is evidence that two of them, MARK1 and MARK4, are involved in the epithelial-to-mesenchymal transition, which is important in tumour metastasis." (PMID 33375416, 2020). "In addition, comparison of metastatic and primary lesions form the same patients revealed that MARK4 expression was increased in secondary as compared to primary tumours in 41% of cases." (PMID 26882547, 2016). "We showed that MARK4 silencing reproduces the morphological and cell migration changes observed following miR‐515‐5p overexpression in both breast and NSCLC cells, demonstrating this to be a consistent phenomenon across two separate tumour types." (PMID 26882547, 2016).
cardiovascular disease (2 papers, 2024 to 2025). "Taken together, our findings demonstrate that MARK4 expression is highly increased in the myocardium of cardiovascular high-risk patients, suggesting it is a potential molecular target against cardiovascular diseases." (PMID 40332117, 2025).
metabolic disease (2 papers, 2016 to 2024). A congenital disorder (due to inherited enzyme abnormality) or acquired (due to failure of a metabolically important organ) disorder resulting from an abnormal metabolic process. "Thus, our study indicated that Mark4 was a potential drug target for treating metabolic diseases." (PMID 26888669, 2016).
brain disease (1 paper, 2025). "This is congruent with the results of previous studies in mice with ischaemic heart and brain disease that observed increased levels of MARK4 with subsequently reduced cell viability." (PMID 40332117, 2025).
inflammation (1 paper, 2016). Aberrant reaction of the microcirculation characterized by movement of fluid and leukocytes from the blood into extravascular tissues. "Moreover, we find that PPARγ is a novel transcriptional suppressor of Mark4 and it alleviates oxidative stress and adipose inflammation by binding to Mark4 promoter region." (PMID 26888669, 2016).
MARK4 also shares sentences with these, for which no sentence is quoted: Insulin resistance (3 papers); neurological disorders (2); acute myocardial infarction (1); adenocarcinoma (1); arterial hypertension (1); Atherosclerotic lesion (1); dementia (1); gastric cancer (1); hyperlipidemia (1); infarction (1); metabolic syndrome (1); metastatic cancer (1); multiple sclerosis (1); non-small cell lung carcinoma (1); osteoarthritis (1); rheumatoid arthritis (1).